CCNE1 (cyclin E1)
Description:
Essential for the control of the cell cycle at the G1/S (start) transition.
Synonyms: CCNE; pCCNE1
Tractability: Small molecule: a structure with a bound ligand is known; a high-quality ligand is known; it belongs to a druggable protein family. PROTAC: UniProt records ubiquitination sites on it; a small molecule that binds it is known.
Target class: Other cytosolic protein
Chemical probes: PD081939, PD083710, PD084111
Gene: Protein-coding gene on chromosome 19 (29,811,471 to 29,824,313, forward strand). Ensembl gene ENSG00000105173.
Subcellular location: Nucleus
Subcellular location (Human Protein Atlas): Nucleoplasm; Cytosol
Pathways (Reactome):
Cell Cycle: Cyclin D associated events in G1; Cyclin E associated events during G1/S transition; G0 and Early G1; G1/S-Specific Transcription; Phosphorylation of proteins involved in G1/S transition by active Cyclin E:Cdk2 complexes; SCF(Skp2)-mediated degradation of p27/p21
Signal Transduction: PTK6 Regulates Cell Cycle; RHOBTB3 ATPase cycle
Cellular responses to stimuli: DNA Damage/Telomere Stress Induced Senescence
DNA Replication: CDK-mediated phosphorylation and removal of Cdc6
Disease: Defective binding of RB1 mutants to E2F1,(E2F2, E2F3)
Metabolism of proteins: Association of TriC/CCT with target proteins during biosynthesis
Gene Ontology:
Molecular function: protein binding; cyclin-dependent protein serine/threonine kinase regulator activity; kinase activity; protein kinase binding
Biological process: G1/S transition of mitotic cell cycle; positive regulation of mesenchymal stem cell proliferation; protein phosphorylation; positive regulation of G1/S transition of mitotic cell cycle
Cellular component: cyclin E1-CDK2 complex; nucleoplasm; nucleus; cytosol; microtubule organizing center; cyclin-dependent protein kinase holoenzyme complex
Genetic constraint (gnomAD): Loss-of-function variants: 10 observed, 46.36 expected, observed/expected ratio (o/e) 0.22, 90% interval 0.13 to 0.37. The upper end of that interval is the gene's LOEUF score, 0.37, which puts it in group 1 of 6, group 1 being the genes least tolerant of losing a copy. Missense variants: 384 observed, 455.36 expected, observed/expected ratio (o/e) 0.84, 90% interval 0.77 to 0.92. Synonymous variants: 155 observed, 168.01 expected, observed/expected ratio (o/e) 0.92, 90% interval 0.81 to 1.05.
Cancer hallmarks: cell replicative immortality (promotes); proliferative signalling (promotes)
Homologues: Orthologues: chimpanzee CCNE1 (99% identical), macaque CCNE1 (98% identical), dog CCNE1 (85% identical), guinea pig CCNE1 (85% identical), rat Ccne1 (80% identical), mouse Ccne1 (79% identical), tropical clawed frog ccne1 (60% identical), zebrafish ccne1 (58% identical), Drosophila melanogaster CycE (42% identical), Caenorhabditis elegans cye-1 (25% identical), Drosophila melanogaster CycB (19% identical), Caenorhabditis elegans cyb-1 (19% identical), and 4 more. Paralogues in human: CCNE2 (48% identical), CCNB1 (22% identical), CCNB2 (21% identical), CCNA1 (20% identical), CCNA2 (20% identical), CCNB3 (18% identical), CCNF (16% identical), CCNI (16% identical), CCND1 (15% identical), CCND2 (15% identical), CCND3 (15% identical), CCNO (15% identical), and 6 more.
Diseases named in the same sentence as CCNE1 in open-access papers:
CCNE1 is named in the same sentence as 177 diseases in open-access papers, as found by Europe PMC text mining. Sharing a sentence is not in itself a finding about the gene and the disease. The quoted sentences say what the papers report.
breast carcinoma (150 papers, 2006 to 2025). "CCNE1, a member of the cyclin family, was reportedly involved in cell cycle progression in breast cancer patients, since higher expression was associated with clinical resistance to a CDK4/6 inhibitor." (PMID 40022573, 2025). "CCNE1 amplification has also been linked to therapeutic resistance to trastuzumab in breast cancer and gastric cancer." (PMID 38717153, 2024). "For instance, overexpression of the proto-oncogene CCNE1, encoding Cyclin E1, which among breast cancers primarily occurs in TNBCs, has been shown to induce replication stress, mitotic aberrancies, and genomic instability." (PMID 38167507, 2024). "Next, gene expression analysis of 302 ER+ breast cancer samples from PALOMA-3 trial revealed that lower Cyclin E1 (CCNE1) mRNA levels were associated with a better response to palbociclib." (PMID 36900131, 2023). "Among HR+ breast cancer patients who progressed on ET, high CCNE1 expression was previously shown to be associated with lower efficacy of palbociclib plus fulvestrant." (PMID 37475004, 2023). "Since 19q12 (CCNE1) amplification is associated with poor survival in other cancer types we examined its relationship with overall survival in BRCA1 mutated breast cancer." (PMID 34465787, 2021). "We also explored the mechanisms underpinning high cyclin E1 expression in BRCA1 mutated breast cancer including gene amplification and protein stability." (PMID 34465787, 2021). "In summary, BRCA1 mutated breast cancers were characterized by reduced cyclin E1 T62 phosphorylation and elevated USP28 expression." (PMID 34465787, 2021). "KIT amp, EGFR amp, MET amp and ALK mutation in lung cancer, and CCNE1 amp in breast cancer were curated as resistant information only in the QCII." (PMID 31383922, 2019). "Only within breast cancer cell lines, was CCNE1 gain alone also associated with temsirolimus resistance (P = 0.010; one-tailed t-test)." (PMID 28903445, 2017). "Cyclin E1 overexpression has also been associated with increased resistance to trastuzumab in Her2+ breast cancers." (PMID 29261144, 2017). "Cyclin E1 overexpression in breast cancer is associated with increased tumor grade, estrogen receptor (ER) negative status, progesterone receptor negative status, and proliferative index by Ki67 staining." (PMID 25830480, 2015). "Cell functional studies further showed that overexpression of miR-195-5p inhibited proliferation and colony formation ability, suppressed cell migration and caused G1 phase arrest by targeting CCNE1 in MDA-MB-231 breast cancer cells." (PMID 24402230, 2014). "In summary, overexpression of miR-195-5p inhibited the proliferation and colony formation ability, suppressed migration and caused G1 phase arrest by targeting CCNE1 in MDA-MB-231 breast cancer cells." (PMID 24402230, 2014). "Some SNPs in DNA repair related genes, such as APE1, XRCC1, ERCC1 and XPF were found to be associated with breast cancer susceptibility in Chinese Han population, so did some SNPs in cell-cycle genes such as CCNE1 and CDK2." (PMID 24386390, 2013). "Breast cancer-associated variants have been found in four cell cycle genes including CCNE1 rs997669." (PMID 20932292, 2010). "CCNE1 expression in breast cancer cells has been associated with ER- status, ERBB2 expression, high tumor grade and high proliferation index." (PMID 20932292, 2010). "We have made a similar observation in the breast cancer cell line MCF-7 that cyclin E2 knockdown leads to an increase in cyclin E1 protein levels, although this is associated with decreased overall proliferation." (PMID 20180967, 2010). "Cyclin E1 was present within Cluster #2 and is a known prognostic marker for breast cancer patients; Cyclin E1 is also associated with basal-like breast cancers, which was recapitulated here." (PMID 17663798, 2007).
breast carcinoma (continued). "CCNE1 protein expression may be regulated differently among luminal breast carcinoma patients, which corresponds to the challenges associated with correlating CCNE1 protein and mRNA levels." (PMID 40548926, 2025). "The authors also confirmed the potential role of CCNE1 as a predictive biomarker in an independent validation cohort of breast cancer patients from the preoperative palbociclib study, where high CCNE1 levels were associated with a decreased antiproliferative effect with palbociclib." (PMID 36176758, 2022). "Additionally, we attempted to mechanistically determine if LINC02568 control in breast cancer progression was associated with the miR-874-3p/CCNE1 axis." (PMID 37303942, 2021). "In this study, we examined whether BRCA1 loss and cyclin E1 gain occurred concurrently or independently in breast cancer." (PMID 34465787, 2021). "We examined the expression levels and clinical relevance of CHEK1, CDC25A, CCNE1, hsa‐miR‐195‐5p, and hsa‐miR‐497‐5p in a comprehensive cohort of 217 breast carcinoma patients." (PMID 40548926, 2025). "RBness breast cancers frequently exhibited cyclin E1 (CCNE1) amplifications compared to RB1-defective breast cancers." (PMID 40138429, 2025). "In this study by utilizing multiplexed protein staining and gene expression analysis from clinical datasets we show that a significant number of breast cancer patients harbor high levels of P16INK4A protein in conjunction with cyclin E1." (PMID 39924553, 2025). ",8,9BRD4 is commonly altered in human cancers, and significant amplification is observed together with the known oncogene cyclin E1 (CCNE1) in both ovarian and breast carcinomas." (PMID 40112818, 2025). "In contrast, in breast cancer, LN metastasis is often observed at the early stage of patients with CCNE1 amplification and Rb1 deletion." (PMID 40565509, 2025). "Meanwhile, in this study, the CPTAC dataset was used to explore the expression of CCNE1 protein in breast cancer, hepatocellular carcinoma, head and neck squamous cell carcinoma, ovarian cancer, and lung adenocarcinoma." (PMID 39591374, 2024). "Further studies are still needed to elucidate the level of immune cell infiltration in CCNE1 overexpressed or other kinds of genomically unstable breast cancer." (PMID 38167507, 2024). "For instance, RNAi approaches, such as siRNA and shRNA, have been shown to successfully silence CCNE1 expression, reducing tumor growth in breast cancer." (PMID 39591374, 2024). "Using the Kaplan‒Meier Plotter portal, the correlation between CCNE1 mRNA expression and the prognosis of patients with ovarian cancer, breast cancer, gastric cancer lung cancer, and liver cancer was investigated." (PMID 36964635, 2023). "In high CCNE1‐expressing breast cancer, CCNE1 can be proteolytically cleaved into low‐molecular weight derivatives." (PMID 36572991, 2023). "ILF3 regulates VEGF mRNA stability in breast cancer and modulates cyclin E1 mRNA stability in hepatocellular carcinoma." (PMID 38136312, 2023). "According to the results, patients with high CCNE1 expression had a poorer prognosis than those with low expression in the ovarian cancer, breast cancer, gastric cancer, lung cancer, and liver cancer cohorts." (PMID 36964635, 2023). "In this study, we found that the hub genes CCNE1, PLK1, and SERPINA1 were significantly overexpressed, amplified, and mutated in breast cancer tissues compared with normal tissues." (PMID 36393842, 2022). "Herein, we show that upregulation of CDK6, p-CDK2, and/or cyclin E1 is associated with adaptation and resistance to AI-monotherapy and combined CDK4/6i and ET in ER+ advanced breast cancer." (PMID 36153348, 2022).
breast carcinoma (continued). "In conclusion, the proofs in this study suggest that reduced miR-511-5p was a biomarker event for breast cancer, and CCNE1 and CHEK1 served as potential targets of miR-511-5p to involve the progression of breast cancer." (PMID 35186236, 2022). "The most prevalent genes that were differentially altered in recurrent tumors were the known oncogene DDX5, which has been shown to be frequently amplified in breast cancers, and CCNE1, which is frequently amplified in HGSOC." (PMID 35883104, 2022). "Next, we examined the association between cyclin E1 expression and overall survival in germline BRCA1 mutated breast cancers in our cohort." (PMID 34465787, 2021). "Previous studies have shown that the co-amplification of CCNE1 and ERBB2 is associated with trastuzumab resistance in breast cancer and GC64,76." (PMID 34168152, 2021). "qRT-PCR were performed to test CCNE1 mRNA expression in collected clinic samples of TNBC, luminal-type breast cancer, and corresponding normal tissues and CCNE1 expressed highest level in TNBC." (PMID 33791304, 2021). "In conclusion, the tumor-promoting functions of LINC02568 in breast cancer cells were enhanced by sequestering miR-874-3p and consequently over-expressing CCNE1." (PMID 37303942, 2021). "Cyclin E1 (CCNE1) promotes progression in breast cancer, but its role and inherent mechanisms in TNBC are yet to be elucidated." (PMID 33791304, 2021). "For breast cancer, overexpression of CCNE1 have been verified as an early event of breast cancer progression, and high level of CCNE1 is often associated with poor prognosis." (PMID 33791304, 2021). "For example, in general, basal-like breast carcinoma has been known to harbor mutations involving BRCA1, CCNE1, AKT3, or MYC; however, these genes were largely wild type, and NOTCH1 mutations were relatively common in our SeC-EOs." (PMID 34638295, 2021). "Analyzing the TCGA BRCA database, CCNE1 was found to be the highest expression in TNBC compared with luminal-type breast cancer and normal samples." (PMID 33791304, 2021). "Combined TCGA BRCA clinical database, we found that breast cancer samples with higher level of T stage or TNM stage show higher expression of CCNE1." (PMID 33791304, 2021). "Overall, germline BRCA1 mutated cancers had significantly higher cyclin E1 protein than the BRCA1 wildtype cases, and tumors with other breast cancer associated germline mutations (BRCA2, PALB2, or CHEK2)." (PMID 34465787, 2021). "As a member of the cyclin family, CCNE1 appears to be controlled by the LINC02568/miR-874-3p axis in breast cancer cells." (PMID 37303942, 2021). "In conclusion, the tumor-promoting role of LINC02568 in breast cancer cells was mediated by sequestering miR-874-3p and subsequently overexpressing CCNE1." (PMID 37303942, 2021). "High expression of CCNE1 in breast cancer, liver cancer, and ovarian cancer indicates poor prognosis." (PMID 33791304, 2021). "For example, upregulated CCNE1, TTK and EXO1 displayed good diagnostic efficacy for screening breast cancer and BRCA1/2-mutant breast cancer." (PMID 31998560, 2020). "It has been found that the expression of miR-30c-2-3p negatively regulates nuclear factor kappa B signaling and cell cycle progression in breast cancer cells via targeting TNFRSF1A-associated via death domain (TRADD) and cyclin E1 (CCNE1), respectively." (PMID 32977589, 2020). "Overexpression of cyclin E1 has been recognized in various malignancies including lung cancer (51%–62%), breast cancer (53%–61%), liver cancer (36%–68%) and some sarcomas (29%–61%)." (PMID 33282745, 2020). "CCNE1, NPBWR1, A2ML1, EXO1 and TTK displayed good prognostic/diagnostic value for breast cancer and BRCA1/2-mutant breast cancer." (PMID 31998560, 2020).
breast carcinoma (continued). "High levels of cyclin E1 were found in hormone receptor positive breast cancer cell lines with acquired resistance to palbociclib and the cyclin E1/Rb ratio was proposed as a marker for palbociclib resistance." (PMID 33255177, 2020). "In a further study, miR-15a and miR-16 expression was significantly downregulated in tamoxifen-resistant breast cancer cells and were able to enhance apoptosis via regulation of both Cyclin E1 and BCL2 expression." (PMID 35582270, 2019). "This study aims to explore the mechanism of Circular RNA CDR1as implicating in regulating 5‐fluorouracil (5‐FU) chemosensitivity in breast cancer (BC) by competitively inhibiting miR‐7 to regulate CCNE1." (PMID 30884120, 2019). "Cluster 3 (CCNE1 and MYBL2) has the same pattern of expression as Clusters 1 and 2 in breast cancer patients and is associated with regulation of cell cycle phase transition GO term." (PMID 31260503, 2019). "Analysis of four independent breast cancer datasets showed that SALL2 mRNA inversely correlates with CCNE1 mRNA levels." (PMID 29689621, 2018). "In another study, CCNE1 was amplified in only five of 16 primary breast carcinomas harbouring amplification of the 19q12 locus." (PMID 27582547, 2017). "CCNE1-amplified breast cancer cells were sensitive to CDK2 inhibitors, resulting in reduced cancer cell survival." (PMID 27582547, 2017). "The known interaction of CDK2 and Cyclin E1 was examined and positive foci were observed in both the nucleus and cytoplasm of T47D breast cancer cells." (PMID 29146920, 2017). "Over-expression of CCNE1 has been detected in various cancers, and recent studies have revealed that miR-497 can directly reduce the CCNE1 protein level to suppress tumor growth by inducing G1 arrest in breast cancer and HCC." (PMID 27344185, 2016). "The RBP HuR is overexpressed in primary breast tumors and breast cancer cells, where it stabilizes cyclin E1 mRNA, leading to cyclin E1 protein overexpression." (PMID 25830480, 2015). "It was also reported that high expression of Cyclin E1 was a strong predictor of endocrine therapy failure in human breast cancer." (PMID 26397135, 2015). "Further analysis of its targets and upstream regulatory mechanism showed that highly expressed E2F7 represses miR-15a/16 expression, which then up-regulates Bcl-2 and Cyclin E1 to induce tamoxifen resistance of breast cancer cells." (PMID 26397135, 2015). "Since both HuR and miRNAs regulate cyclin E1 and both are deregulated in breast cancer, we set out to determine if HuR and miR-16 cooperate to control cyclin E1 level in breast cancer cells." (PMID 25830480, 2015). "CCNE1 amplification is reported in up to 24% of HER2-positive breast cancers and it has been suggested to play a role during trastuzumab resistance in breast cancer." (PMID 25786580, 2015). "Despite the relevance of cyclin E2 to breast cancer biology, the vast majority of studies defining the regulatory mechanisms that control type-E cyclins has been dedicated only to cyclin E1." (PMID 25596745, 2015). "Here, we show that in breast cancer cells, cyclin E1 upregulation by the RBP HuR is through specific binding to regions in the cyclin E1 mRNA 3' untranslated region (3'UTR) containing U-rich elements." (PMID 25830480, 2015). "In breast cancer, cyclin E1 is overexpressed in 30% of patients, including overexpression of both the full length (50 kDa) and several LMW isoforms (ranging in size from 33 to 45 kDa)." (PMID 25830480, 2015). "Over expression of CCNE1 in many human tumors including leukaemia, breast cancer and others, has been reported." (PMID 24409284, 2014). "CCNE1 is overexpressed in many human tumors, in particular, breast cancer, and also nonsmall cell lung cancer, leukemia, and others." (PMID 24605326, 2014).